IGKV1-12 (immunoglobulin kappa variable 1-12)
Description:
V region of the variable domain of immunoglobulin light chains that participates in the antigen recognition. Immunoglobulins, also known as antibodies, are membrane-bound or secreted glycoproteins produced by B lymphocytes. In the recognition phase of humoral immunity, the membrane-bound immunoglobulins serve as receptors which, upon binding of a specific antigen, trigger the clonal expansion and differentiation of B lymphocytes into immunoglobulins-secreting plasma cells. Secreted immunoglobulins mediate the effector phase of humoral immunity, which results in the elimination of bound antigens. The antigen binding site is formed by the variable domain of one heavy chain, together with that of its associated light chain. Thus, each immunoglobulin has two antigen binding sites with remarkable affinity for a particular antigen. The variable domains are assembled by a process called V-(D)-J rearrangement and can then be subjected to somatic hypermutations which, after exposure to antigen and selection, allow affinity maturation for a particular antigen.
Synonyms: IGKV112; L19
Gene: Immunoglobulin variable (V) gene on chromosome 2 (89,040,224 to 89,040,745, reverse strand). Ensembl gene ENSG00000243290.
Subcellular location: Secreted; Cell membrane
Pathways (Reactome):
Immune System: Antigen activates B Cell Receptor (BCR) leading to generation of second messengers; CD22 mediated BCR regulation; Classical antibody-mediated complement activation; FCERI mediated Ca+2 mobilization; FCERI mediated MAPK activation; FCERI mediated NF-kB activation; FCGR activation; Fc epsilon receptor (FCERI) signaling; Immunoregulatory interactions between a Lymphoid and a non-Lymphoid cell; Initial triggering of complement; Regulation of Complement cascade; Regulation of actin dynamics for phagocytic cup formation; Role of LAT2/NTAL/LAB on calcium mobilization; Role of phospholipids in phagocytosis
Disease: FCGR3A-mediated IL10 synthesis; FCGR3A-mediated phagocytosis; Potential therapeutics for SARS
Hemostasis: Cell surface interactions at the vascular wall
Vesicle-mediated transport: Scavenging of heme from plasma
Gene Ontology:
Biological process: immune response
Cellular component: extracellular region; immunoglobulin complex; plasma membrane
Homologues: Orthologues: mouse Igkv15-103 (75% identical). Paralogues in human: IGKV1D-12 (99% identical), IGKV1D-16 (93% identical), IGKV1-39 (91% identical), IGKV1-9 (91% identical), IGKV1D-13 (91% identical), IGKV1D-39 (91% identical), IGKV1-16 (91% identical), IGKV1-17 (91% identical), IGKV1-27 (90% identical), IGKV1-5 (89% identical), IGKV1-6 (89% identical), IGKV1D-17 (88% identical), and 81 more.